Y_RNA (Y RNA )
Gene: Miscellaneous RNA gene on chromosome 17 (32,463,374 to 32,463,482, reverse strand). Ensembl gene ENSG00000202100.
Homologues: Orthologues: chimpanzee Y_RNA (99% identical), guinea pig Y_RNA (88% identical), guinea pig Y_RNA (86% identical). Paralogues in human: RNY1 (88% identical), Y_RNA (87% identical), Y_RNA (86% identical), Y_RNA (85% identical), Y_RNA (84% identical), Y_RNA (83% identical), RNY1P11 (83% identical), RNY1P7 (82% identical), RNY1P8 (82% identical), Y_RNA (82% identical), RNY1P15 (81% identical), Y_RNA (81% identical), and 96 more.